IRS4 (insulin receptor substrate 4)
Description:
Acts as an interface between multiple growth factor receptors possessing tyrosine kinase activity, such as insulin receptor, IGF1R and FGFR1, and a complex network of intracellular signaling molecules containing SH2 domains. Involved in the IGF1R mitogenic signaling pathway. Promotes the AKT1 signaling pathway and BAD phosphorylation during insulin stimulation without activation of RPS6KB1 or the inhibition of apoptosis. Interaction with GRB2 enhances insulin-stimulated mitogen-activated protein kinase activity. May be involved in nonreceptor tyrosine kinase signaling in myoblasts. Plays a pivotal role in the proliferation/differentiation of hepatoblastoma cell through EPHB2 activation upon IGF1 stimulation. May play a role in the signal transduction in response to insulin and to a lesser extent in response to IL4 and GH on mitogenesis. Plays a role in growth, reproduction and glucose homeostasis. May act as negative regulators of the IGF1 signaling pathway by suppressing the function of IRS1 and IRS2.
Synonyms: IRS-4; py160; CHNG9
Tractability: Antibody: UniProt places it where antibodies can reach, with high confidence; its Gene Ontology location is reachable by antibodies, with high confidence. PROTAC: UniProt records ubiquitination sites on it; ubiquitination databases record sites on it.
Gene: Protein-coding gene on chromosome X (108,719,946 to 108,736,563, reverse strand). Ensembl gene ENSG00000133124.
Subcellular location: Cell membrane
Pathways (Reactome):
Signal Transduction: IRS-related events triggered by IGF1R
Gene Ontology:
Molecular function: protein binding; transmembrane receptor protein tyrosine kinase adaptor activity; insulin receptor binding
Biological process: insulin receptor signaling pathway; insulin-like growth factor receptor signaling pathway; phosphatidylinositol 3-kinase/protein kinase B signal transduction; signal transduction
Cellular component: cytosol; plasma membrane
Cancer hallmarks: change of cellular energetics; escaping immune response to cancer (suppresses); escaping programmed cell death (promotes); proliferative signalling (promotes); invasion and metastasis (promotes)
Homologues: Orthologues: chimpanzee IRS4 (99% identical), macaque IRS4 (89% identical), pig IRS4 (87% identical), dog IRS4 (84% identical), guinea pig IRS4 (77% identical), mouse Irs4 (77% identical), rabbit IRS4 (75% identical), rat AABR07040887.1 (73% identical), tropical clawed frog irs4 (27% identical), zebrafish irs4a (21% identical), Drosophila melanogaster chico (14% identical). Paralogues in human: IRS2 (26% identical), IRS1 (25% identical).
Diseases named in the same sentence as IRS4 in open-access papers:
IRS4 is named in the same sentence as 55 diseases in open-access papers, as found by Europe PMC text mining. Sharing a sentence is not in itself a finding about the gene and the disease. The quoted sentences say what the papers report.
Insulin resistance (9 papers, 2010 to 2025). Increased resistance towards insulin, that is, diminished effectiveness of insulin in reducing blood glucose levels. "Among these, Irs4 is directly associated with insulin resistance." (PMID 38396669, 2024). "But it is unknown whether IRS4 are related to HCV-associated insulin resistance." (PMID 29285303, 2017). "Among the four mammalian IRS proteins (IRS-1, IRS-2, IRS-3, IRS-4), IRS-1 and IRS-2 are considered key nodes in the insulin signaling system, and their dysfunction is closely linked to the development of insulin resistance." (PMID 39966707, 2025). "Among the six mammalian IRS proteins (IRS-1, IRS-2, IRS-3, IRS-4, IRS-5, IRS-6), IRS-1 and IRS-2 are typically considered key nodes in the insulin signaling system, closely associated with the development of insulin resistance." (PMID 39966707, 2025). "Irs4−/− mice are phenotypically normal, with only mild insulin resistance and growth and reproductive defects, in keeping with the more restricted expression pattern of IRS-4." (PMID 36556357, 2022). "IRS4 is part of insulin signaling pathway and its upregulation can lead to insulin resistance." (PMID 40473938, 2025). "Report showed that PP4C could interact with IRS-4 and down-regulate IRS-411, we wondered whether PP4 was involved in TNF-α-induced insulin resistance by interacting with IRS-1." (PMID 26666849, 2015).
breast carcinoma (6 papers, 2016 to 2024). "The present study will review IRS4, which has been implicated in some types of cancer, such as breast cancer, squamous carcinoma of the lung, sarcomas, and acute lymphoblastic leukaemia." (PMID 32211045, 2020). "Our data establish Irs4 as a potent oncogene in mouse mammary tumorigenesis and we show that IRS4 expression in human primary breast cancers is associated with poor survival." (PMID 27876799, 2016). "This urged us to investigate whether IRS4-mediated constitutive PI3K/AKT pathway activation causes resistance to HER2-targeting drugs in HER2+ breast cancer cell lines." (PMID 27876799, 2016). "Although one of the least characterized proteins in this family, IRS4 has been associated with the hyperactivation of the mTOR and ERK pathways in lung and breast cancer." (PMID 37894790, 2023). "In both triple-negative and HER2+ breast cancers, IRS4 expression is most likely an additional mechanism to activate the PI3K/AKT pathway and consequently, tumorigenesis." (PMID 27876799, 2016). "We examined IRS4 expression in a random set of 27 human primary breast carcinomas and found five (19%) positive samples, of which four (15%) were highly positive." (PMID 27876799, 2016). "In search of oncogenic drivers and mechanisms affecting therapy resistance in breast cancer, we identified Irs4, a poorly studied member of the insulin receptor substrate (IRS) family, as a mammary oncogene by insertional mutagenesis." (PMID 27876799, 2016). "In this study, the authors identified IRS4 as a potential oncogene in breast cancer that leads to the constitutive activation of PI3K/AKT signalling and thus confers resistance to HER2-targeted therapy." (PMID 27876799, 2016). "In a clinically relevant setting, we moreover demonstrate that treatment of breast cancer cells with suboptimal doses of these HER2-targeting drugs consistently results in selection of cells with upregulated IRS4-levels, in particular with Lapatinib." (PMID 27876799, 2016). "Taken together, our findings present the cellular and molecular mechanisms of IRS4-induced tumorigenesis and establish IRS4 as an oncogenic driver and biomarker for therapy resistance in breast cancer." (PMID 27876799, 2016). "Further investigating the involvement of IRS4 in human breast cancer, we performed a knockdown of the endogenous IRS4 in these cancer cells and observed a concomitant reduction in PI3K/AKT pathway activation and cell growth." (PMID 27876799, 2016). "Whereas normally silent in the postnatal mammary gland, IRS4 is found to be highly expressed in a subset of breast cancers." (PMID 27876799, 2016). "Ectopic expression of Irs4 in human HER2+ breast cancer cell lines SKBR3 and BT474, clearly induced resistance to Trastuzumab and Lapatinib." (PMID 27876799, 2016). "Next, we demonstrate that IRS4 is expressed in a subset of human breast cancers, collaborates with HER2 to drive tumorigenesis, and confers resistance to HER2-targeted therapy." (PMID 27876799, 2016). "In line with this clinical data, the two IRS4-positive human breast cancer cell lines we identified, MDA-MB-453 and HCC187, are both of the triple-negative subtype." (PMID 27876799, 2016). "To confirm that this resistance is due to PI3K/AKT pathway hyperactivation, we treated the Irs4-transduced HER2+ breast cancer cell lines with a combination of Trastuzumab or Lapatinib and the PI3K-inhibitor GDC0941." (PMID 27876799, 2016). "However, in breast cancer cells, IRS4 can induce constitutive PI3K/AKT hyperactivation even in the absence of insulin or growth factors." (PMID 39227585, 2024). "Similarly, drivers of oncogenesis in breast cancer and AML, IRS4, and MN1 are mutated and downregulated." (PMID 37091785, 2023). "Moreover, one of the four highly IRS4-positive samples in the random set of 27 human primary breast carcinomas was also one of the four ERBB2-positive samples." (PMID 27876799, 2016).
breast carcinoma (continued). "Also, IRS4 expression was only observed in two of 25 tested human breast cancer cell lines, MDA-MB-453 and HCC187 cells, and in HEK293 cells." (PMID 27876799, 2016). "In the light of our finding that IRS4 is constitutively active, these data strongly point to a role for IRS4 as oncogene in human breast cancer, which may particularly be true in the triple-negative and HER2-positive subtypes." (PMID 27876799, 2016). "To assess whether IRS4-mediated resistance would occur spontaneously in HER2+ breast cancer cell lines, we cultured naive cell lines for five passages in medium containing increasing concentrations of Trastuzumab or Lapatinib." (PMID 27876799, 2016). "Hence, knockdown of Irs4 abolished the tumorigenic potential of these mammary tumour cells, showing that the cells are dependent on IRS4 for tumour growth in vivo." (PMID 27876799, 2016). "To expand these data, we screened for IRS4 expression in an independent uniform HER2-positive and an independent uniform triple-negative human breast cancer series by quantitative RT–PCR (qRT–PCR)." (PMID 27876799, 2016). "For example, overexpression of insulin receptor substrate 4 (IRS4) drives a subset of breast cancers, while IRS1 and IRS2 are not oncogenic in these cancers, even though all three IRS proteins activate PI 3-kinase–Akt growth signalling." (PMID 28928963, 2017).
Central hypothyroidism (6 papers, 2020 to 2023). A type of hypothyroidism due to an insufficient stimulation of an otherwise normal thyroid gland. "FAM47A and TFE3 were potential risk genes for hypertension, whereas IRS4, an insulin signaling-pathway gene associated with central hypothyroidism, potentially linked with cardiac defects." (PMID 37800145, 2023). "Mutations in IRS4 are associated with central hypothyroidism, and the TSH response to the TRH test is blunted in male IRS4 mutation carriers having central hypothyroidism." (PMID 34828419, 2021). "Five male probands from unrelated families with pathogenic variants in the insulin receptor substrate-4 gene (IRS4) (OMIM #300904) had a phenotype consisting of solely X-linked central hypothyroidism and an abnormal TSH response to exogenous TRH." (PMID 34566885, 2021). "In humans, mutations in IRS4 are associated with central hypothyroidism, although mice carrying an Irs4 null allele had unchanged serum thyroid hormone concentrations." (PMID 32371981, 2020). "Indeed, fasted subjects (an example of subjects with reduced leptin signaling) have similar TSH secretion patterns and TRH test results as patients with central hypothyroidism due to IRS4 loss-of-function." (PMID 34566885, 2021). "In summary, our data from patients with a novel frameshift mutation in IRS4 gene together with the observed association between the rare IRS4 haplotype and thyroid disease risk supports the pathogenic role of IRS4 in isolated central hypothyroidism." (PMID 34093435, 2021). "A pathophysiological mechanism of central hypothyroidism due to IRS4 dysfunction incorporating pituitary TRH resistance or defective TSH transcription/post-translational modification is conceivable." (PMID 34566885, 2021). "However, patients with leptin deficiency and leptin resistance invariably present with central hypothyroidism, and have a different TSH secretion pattern in response to exogenous TRH than patients with IRS4 loss-of-function." (PMID 34566885, 2021). "The five genes associated with isolated congenital central hypothyroidism are thyrotropin-releasing hormone receptor gene (TRHR), thyroid-stimulating hormone β-subunit gene (TSHB), and the more recently described genes IGSF1, TBL1X, and IRS4." (PMID 33585976, 2021). "Our findings confirm the role of IRS4 in isolated central hypothyroidism." (PMID 34093435, 2021). "The data from this family supports the pathogenic role of IRS4 in isolated central hypothyroidism and the cases showed no obvious additional phenotypes." (PMID 34093435, 2021).
colorectal cancer (6 papers, 2018 to 2024). A primary or metastatic malignant neoplasm that affects the colon or rectum. "IRS4 expression has been associated with cell proliferation, and its overexpression has been correlated with the development and staging of colorectal cancers." (PMID 39199837, 2024). "The X‐linked cancer‐related genes FLNA, TBX22, KIAA2022, IRS4, PCDH11X, and GPR112 are connected to colorectal cancer." (PMID 38827026, 2024). "X‐linked FLNA, TBX22, KIAA2022, IRS4, PCDH11X, GPR112, and F8 have been proposed as cancer‐related genes in colorectal cancer." (PMID 38827026, 2024). "IRS4 is overexpressed in colorectal cancer, and when overexpressed in RKO cells, it induces the expression of cyclin D1, Cyclin E, E2F1, and pRB Ser 705 and pRB Ser809/811 genes." (PMID 37686244, 2023). "We reported that insulin receptor substrate 4 (IRS-4) levels increased in tissue from colorectal cancer (CRC) patients and promoted retinoblastoma-cyclin-dependent kinase activation." (PMID 30410539, 2018). "Both IGF2 and IRS4 were initially discovered by CESAM as enhancer hijacking target genes using CNV breakpoints profiled by microarray with much larger sample sizes (378 colorectal cancers and 497 lung squamous cell carcinomas)." (PMID 39051548, 2024). "Likewise, the expression of IRS-4 was also related to the activation of Cyclin D1 and Rb1 in colorectal cancer, two markers also altered in our study." (PMID 35743985, 2022). "Increased IRS-4 levels were found in the remnant liver after partial hepatectomy, as well as in uterine leiomyomas, subungual exostosis, breast cancer, hepatocellular carcinoma, leukaemia, lung cancer, and colorectal cancer." (PMID 30410539, 2018). "In addition we showed that overexpression of IRS-4 correlated with clinical staging in colorectal cancer patients." (PMID 30410539, 2018).
melanoma (6 papers, 2012 to 2024). A malignant, usually aggressive tumor composed of atypical, neoplastic melanocytes. "IRS4 overexpression has been associated with acute lymphoblastic leukaemia and subungual exostosis, while point mutations of IRS4 have been found in melanomas." (PMID 24039912, 2013). "IRS4 has recently been documented to be mutated in melanoma." (PMID 23006971, 2012). "Specifically, the role of IRS-4 in different types of digestive tract neoplasms, gynecological tumors, lung cancers, melanomas, hematological tumors, and other less common types of cancers has been shown." (PMID 37760618, 2023). "The overexpression of IRS-4 in melanoma has been attributed to a decrease in microRNA-493 (miR-493), which is involved in IRS-4 mRNA destabilization." (PMID 34577545, 2021). "Recent studies in melanoma have indicated that some components of the PI3K pathway (PTEN, MTOR, IRS4, PIK3R1, PIK3R4, PIK3R5 and NFKB1) are co-mutated in 17% of BRAF V600E mutant and 9% of NRAS mutant melanomas." (PMID 23006971, 2012). "Recently, it has been demonstrated that evodiamine, a novel alkaloid isolated from the fruit of tetradium, significantly inhibits the growth of vemurafenib-resistant melanoma cells by inhibiting the PI3K/Akt signaling pathway through the suppression of IRS4 (insulin receptor substrate 4)." (PMID 39199632, 2024).
hepatocellular carcinoma (5 papers, 2009 to 2022). A malignant tumor that arises from hepatocytes. "In HepG2 hepatocellular carcinoma cells, suppression of IRS-4 expression by siRNA decreases IGF-1-dependent proliferation, which correlates with reduced Erk and p70S6-kinase activation." (PMID 19534786, 2009). "To date, the only study to examine IRS-4 expression in human cancer reported increased expression in hepatocellular carcinoma." (PMID 19534786, 2009). "We used immunohistochemistry to examine IRS-4 expression in biopsies of tumoral tissue from a cohort of 31 patient suffering of hepatocellular carcinoma (HCC)." (PMID 34071030, 2021).
lung carcinoma (4 papers, 2021 to 2024). "However, some data reveal that IRS-4 overexpression is associated with recurrent deletions in cis-regulatory elements in lung cancer; similarly, chromosome translocations in T cells have been observed, which involves IRS-4 gene induction in acute lymphoblastic leukemia." (PMID 34071030, 2021). "In addition, previous studies have also found an association between the activation of PI3K/Akt and other pathways such as Ras-MAPK by IRS-4 with therapeutic resistance and tumor progression in lung cancer." (PMID 35743985, 2022). "In contrast, IRS-4 has been shown to be overexpressed in benign proliferative lesions such as uterine leiomyomas and subungual exostosis, as well as in malignant diseases such as breast cancer, leukemia, lung cancer, and colorectal cancer." (PMID 34071030, 2021). "For instance, eliminating CTCF insulator sites at TAD borders in lung cancer enabled the spreading of active chromatin to a merged TAD, forming an IRS4 SE that drove oncogenic IRS4 overexpression." (PMID 38844984, 2024).
Alzheimer disease (3 papers, 2013 to 2025). A progressive, neurodegenerative disease characterized by loss of function and death of nerve cells in several areas of the brain leading to loss of cognitive function such as memory and language. "Finally, insulin signaling, in particular the down-regulation of the insulin receptor substrate 4 (Irs4) gene, may be an important event in the transition from age-related changes to Alzheimer’s disease specific-changes." (PMID 24274089, 2013).
leiomyoma (3 papers, 2023 to 2025). A well-circumscribed benign smooth muscle neoplasm characterized by the presence of spindle cells with cigar-shaped nuclei, interlacing fascicles, and a whorled pattern. "IRS4 overexpression has been previously observed in leiomyomas harboring COL4A5-COL4A6 deletions." (PMID 41162745, 2025). "For comparison of differential expression of genes in leiomyomas, there was a significant race/ethnicity correlation in expression for TNFRSF19, IRS4, PLEKHG4B, PGR, KRT17, CCDC177, MYO5B, and ZNF703." (PMID 37686244, 2023).